CRK (CRK proto-oncogene, adaptor protein)
Diseases named in the same sentence as CRK in open-access papers (continued):
Sharing a sentence is not in itself a finding about the gene and the disease.
cancer (40 papers, 2008 to 2025). A tumor composed of atypical neoplastic, often pleomorphic cells that invade other tissues. "Overexpression of CRK or CRKL has been linked to a subset of some cancer types such as ovarian and non-small cell lung cancer." (PMID 27686861, 2016). "CRK is a component of the focal adhesion complex that is involved in integrin signalling and high levels of CRK have been associated with an aggressive phenotype of carcinomas." (PMID 22384141, 2012). "Analysis of the curated set of non-redundant studies in The Cancer Genome Atlas (TCGA) using the cBioPortal platform indicates that only 0.5% and 1% of cancer patients showed copy number increases for CRK and CRKL, respectively." (PMID 33801580, 2021). "Tyrosine phosphorylated CagA by SRC family kinases interacts with SHP2 tyrosine phosphatase (encoded by the PTPN11 oncogene), CRK, CRKL and CSK and induces cell scattering, dissociation and mortality connected to cancer development." (PMID 22383989, 2012). "CRK is overexpressed in various cancers, and its expression often correlates with tumor grade." (PMID 38183097, 2024). "Additional structural studies between ELMO:DOCK complexes and CRK adapters may reveal novel mechanisms of activation of these GEFs that could be targetable in anti‐cancer efforts." (PMID 36271211, 2023). "CRK has been shown to play a role in cancer progression and malignant behavior." (PMID 34888227, 2021). "However, CXCR4 also activates RAS/MAPK, PI3-kinase/AKT, and CRK signaling, which is particularly well documented in cancer cells." (PMID 34350830, 2021). "MiR-126 alters the biological functions of some genes such as PI3K, EGFL7, HOXA9, sKRAS, CRK, ADAM9, IRS-1, SOX-2, SLC7A5, and VEGF, as well as involves in inflammation, cell migration, angiogenesis, recurrence of cancer, and metastasis." (PMID 38445462, 2024). "Many targets of miR-126 were experimentally validated in other cancer types, including VEGF-A28, ADAM929, Sox230, CRK, and PI3KR231." (PMID 28600498, 2017). "Therefore, the differentially methylated specific genes (NTRK2, MAPKAPK2, CRK, and NFATC2) and the dysregulated miRNAs (mir-148a, mir-374a and mir-494) in the MAPK and ErbB pathways cause cell proliferation, adhesions and migration and the immune cell infiltration to cancer cells during early HCC." (PMID 27821810, 2016). "CRK and CRKL adapter proteins play essential roles in development and cancer through their SRC homology 2 and 3 (SH2 and SH3) domains." (PMID 27686861, 2016). "More recently, miR-126 down-regulation has been linked to RCC progression, and has been shown to act as a tumor suppressor in various cancer types including RCC through regulating target genes such as CRK, VEGF, and EGFL7 in cancer cells." (PMID 26416448, 2015). "Recently miR-126 has been reported to be a tumour suppressor in various cancer types including RCC regulating target genes like CRK, VEGF and EGFL7 in cancer cells." (PMID 24428907, 2014). "Those pathways specifically altered in primary tumors were associated with an abnormally increased expression of genes that are involved in focal adhesion (e.g., PRKCA, CRK, and BCL2), PI3K-Akt signaling (e.g., PHLPP2, PRKCA, PPP2R3A and KIT) and cancer pathways (e.g., COL4A5, LAMC1 and BCL2L1)." (PMID 27662660, 2016). "Among central nodes were ERBB2 (v-erb-b2 avian erythroblastic leukemia viral oncogene homolog 2), CRK (Cysteine-rich receptor-like-kinase), HRAS, and KRAS (Kirsten rat sarcoma virus), all of which were proto-oncogenes involved in the development of various cancer types." (PMID 38304545, 2024).
cancer (continued). "However, we found a number of established drivers of cancer progression and invasion (e.g., mTOR, STAT1/5, RHOC, ARF6, HMGB, and CRK) with increased expression levels as well as known suppressors (e.g., AIFL1 and SLIT3) with decreased expression levels upon PTEN inhibition." (PMID 36555834, 2022). "It included a number of genes with obvious cancer relevance including CD44, catenin b1 (CTNNB1), vimentin (VIM), cathepsins B and S (CTSB, CTSS), MMP9, XIAP, JunD, numerous proto-oncogenes (REL, YES, SET, FGR, CRK), and HSP90AA1 (which is a chaperone which stabilizes MIF as a client)." (PMID 28957348, 2017). "Copy number losses of CRK (P = 0.07), SMAD2 (P = 0.09), FHIT (P = 0.68), and NFATC1 (P = 0.11) genes did not vary significantly between diffuse-type cancers and intestinal-type cancers." (PMID 26360582, 2015).
tumor (30 papers, 2009 to 2025). "As a member of the CRK (v‐crk sarcoma virus CT10 oncogene homologue) adapter protein family, CRKL (CRK‐like) associated with the development and progression of various tumours." (PMID 33523562, 2021). "SRC and CRK-associated substrate phosphorylation is an important promoter of PDAC anchorage-independence and tumor progression." (PMID 22384141, 2012). "This suggested that CRK may exert tumor-suppressive functions while CRKL may act as a pro-tumorigenic factor." (PMID 39126118, 2024). "Another possibility is that the complement of downstream Abl kinase substrates such as ABI1 and CRK may influence in which cell types Abl kinases may function as promoters versus suppressors of tumor progression." (PMID 37746268, 2023). "Note, two of the significantly regulated tumour proteins, i.e. CRK and PEBP1 are members of the EGFR1 signalling pathway with PEBP1 also functioning as a master regulator while the other regulated proteins are connected to EGFR signalling through cross-talk among the pathways." (PMID 25872475, 2015). "This identified increased CRK protein levels in PDAC compared to benign tissues and normal, indicating a regulatory role of miR-126 in this tumor type." (PMID 22384141, 2012). "While VASP and RAPH1 expression did not significantly differ between non-tumor and tumor tissue, CRK and CRKL exhibited an opposite expression pattern." (PMID 39126118, 2024). "It was reported that miR-126 was down-regulated in PC tissues and could act as a tumor suppressor in PC by inhibiting ADAM9, KRAS and CRK which was in accordance with our findings." (PMID 27626307, 2016). "Expression in U87-MG and U118 cell lines, PA-NAV, PA-GAS and PA-PET initial tumor specimen and in the excised tumor of the case report: we quantified the ICAM1, CRK, CD36, and IQGAP1 mRNA expression in our in vitro models and in the surgical specimen of the case report." (PMID 24252689, 2013). "Tumor expression levels of miR-126 did not significantly differ between LC-COPD and LC patients, whereas in the former patients, an almost significant decrease in EGFL-7 expression was observed (p = 0.073), together with a decrease in TOM-1 and CRK expression and a rise in angiopoietin-2 content." (PMID 29371906, 2018).
infection (17 papers, 2008 to 2025). The state of being infected such as from the introduction of a foreign agent such as serum, vaccine, antigenic substance or organism. "Many CRK-encoding genes are involved in ROS/redox signaling and sensing, activation of hypersensitive cell death during pathogen infection, enhanced pattern-triggered immunity (PTI), and regulation of PAMP/DAMP." (PMID 39456688, 2024). "In infected wheat cultivars, a consistent pattern of downregulation of specific CRK genes was observed across various developmental stages, highlighting the impact of infection on their expression levels." (PMID 37631144, 2023). "CRK genes are induced upon pathogen infection in A. thaliana via the SA signaling pathway, resulting in HR." (PMID 34532063, 2021). "In this study, we found that the members of the CRK gene family displayed up-regulation following infection by V. dahliae." (PMID 30254650, 2018). "CRK genes have been shown to be induced in plants during pathogen infection, including the upregulation of several CRKs during infection of B. napus cotyledons by L. maculans." (PMID 27553246, 2016). "For understanding the expression profile of the CRK gene family at the germination, penetration, and colonization stages of fungal development on wheat plants, four different time points after infection, 12 hai, as well as 1, 2, and 3 dai, were compared with the preincubation stage." (PMID 37631144, 2023). "Genes linked to STAT3 during infection were associated with GO terms such as regulation of cell proliferation (CCND1, JUNB), negative regulation of apoptosis (MCL-1, NFKB1), cytokine-mediated signaling pathway (IL10RA, SOCS1), and immune system process (CRK, IRF9)." (PMID 41115066, 2025). "In summary, TepP is a C. trachomatis T3S effector recruiting CRK and CRKL adaptor proteins, as well as PI3K, to modulate innate immune signalling early in host cell infection that is likely required for chlamydial growth." (PMID 31528632, 2019). "Our results showed that the CRK expression profile upon O3 exposure was most similar to those stimulated by PAMP perception (flg22 and HrpZ) and pathogen infection (Bgh)." (PMID 20500828, 2010). "Secretion: T3S; targets: CRK, CRKL, PI3K subunits, and GSK3B; localization: cytosol, near the early vacuole; function: modulation of host gene expression related with immune signalling in early stages of infection." (PMID 31528632, 2019).
CRK also shares sentences with these, for which no sentence is quoted: glioblastoma (6 papers); prostate carcinoma (4); ovarian carcinoma (3); Bacterial infection (2); chronic myeloid leukemia (2); glioma (2); hepatocellular carcinoma (2); oral squamous cell carcinoma (2); salivary gland tumor (2); synovial sarcoma (2); acinic cell carcinoma (1); adenocarcinoma (1); adenoid cystic carcinoma (1); Alzheimer disease (1); autism (1); autism spectrum disorder (1); bladder cancer (1); brain tumors (1); breast adenocarcinoma (1); breast tumors (1); Chlamydia infection (1); colorectal cancer (1); DiGeorge syndrome (1); Failure to thrive (1); heart diseases (1); HIV-1 infection (1); influenza (1); irritable bowel syndrome (1); lymphoma (1); Miller-Dieker syndrome (1).
A further 16 diseases each share a sentence with CRK in 1 paper.